CRP (C-reactive protein)
Diseases named in the same sentence as CRP in open-access papers (continued):
Sharing a sentence is not in itself a finding about the gene and the disease.
Cirrhosis (continued). "In contrast, CRP, PCT, and the average levels of IL-6 and IL-10 are higher in ACLF than in patients with decompensated cirrhosis." (PMID 39337069, 2024). "For example, the general laboratory test indices of ascites calprotectin and lactoferrin, serum procalcitonin and C-reactive protein (CRP), platelet and neutrophil-to-lymphocyte ratio (NLR) have been documented in the diagnosis of SBP in cirrhosis." (PMID 37951894, 2023). "Univariate predictors of mortality for the cirrhosis and CDI patients included Child–Pugh score (p-value = 0.026), leukocytes (p-value = 0.023), CRP (p-value = 0.012), Atlas score (p-value = 0.011) and MELD (p-value = 0.022)." (PMID 34204307, 2021). "Many previous studies addressed the usefulness of CRP and PCT as predictors of mortality in cirrhosis, whereas data about the prognostic role of IL-6ascites are rare." (PMID 32899730, 2020). "Leukocytes, MELD-score, INR, creatinine, etiology of cirrhosis, history of SBP, HE, ACLF and CRP were different between nSBP and w/o SBP patients." (PMID 31374111, 2019). "This work is aimed at evaluating and comparing diagnosis and prognosis performance of CRP and PCT during BI in patients admitted for decompensated cirrhosis." (PMID 31582968, 2018). "In patients with cirrhosis, plasma LBP correlated positively with CRP and procalcitonin." (PMID 39997462, 2025). "Unlike other studies, serum TNF-α and CRP were not increased, possibly due to the early stage of cirrhosis and cohort homogeneity, as well as differences in cirrhosis etiology." (PMID 39850960, 2025). "A comparison of the total patient cohort and the subgroup of patients without liver cirrhosis revealed that C-reactive protein (CRP) was higher after the exclusion of patients with cirrhosis." (PMID 39997462, 2025). "From the Hedge’s G values for the three sweat biomarkers, it can be concluded that CRP and IL6 show a significant effect size between evening and night periods in cirrhosis subjects compared to morning periods, while the same significance in effect size is not observed in control subjects." (PMID 39733165, 2024). "Therefore, both CRP and WCC, although useful markers of infection and inflammation in cirrhosis, have weak prognostic values when considered individually." (PMID 37019645, 2023). "It was reported that patients with ACLF had higher white blood cell (WBC) and C-reactive protein (CRP) levels than those with decompensated cirrhosis without ACLF." (PMID 36743413, 2023). "In addition, several inflammation-based markers, such as C-reactive protein (CRP) and neutrophil-to-lymphocyte ratio (NLR), can predict outcomes in patients with cirrhosis." (PMID 36983211, 2023). "The median CRP levels in patients with class Child–Pugh B cirrhosis were not significantly different from median CRP levels in Child–Pugh C cirrhotic patients (3.65 mg/dL vs. 4.01 mg/dL, p = 0.854)." (PMID 36143057, 2022). "Secondly, the study population included patients in different phases of the disease evolution (cirrhosis, early-stage HCC, and metastatic HCC) and the values of AFP, ESR, and CRP may greatly differ at these different stages of the disease." (PMID 35200757, 2022). "Univariate RDA analysis revealed that cirrhosis, PPI intake, beta blockers, statins, platelet function inhibitors, BMI, CRP, INR, calprotectin, zonulin, DAO, lipopolysaccharide-binding protein (LBP) and sCD14 were potential explanatory variables for microbiome composition with a p-value < 0.1." (PMID 32906634, 2020). "Another infection study suggested that serum levels of acute-phase proteins (CRP and procalcitonin) originating from the liver were comparable between patients with and without cirrhosis." (PMID 31821367, 2019). "The progression of cirrhosis and the development of HRS type II may result in positive correlation between MDA and CRP." (PMID 29658815, 2018). "In cirrhosis, the MDA level increased with the rise of CRP (C = 0.77)." (PMID 29658815, 2018).
Cirrhosis (continued). "There is a close correlation between inflammation and HCC47, and in our study CRP levels were higher in the HCC group than in the cirrhosis group, although the difference was not statistically significant." (PMID 27694815, 2016). "A systematic review demonstrated that moderate CRP increases may not predict infections in cirrhosis, but high CRP levels on presentation or persistently high CRP levels may provide better evidence of infection in these patients." (PMID 39961976, 2025). "In cirrhosis, the basal level of CRP is found to be higher than that in non-cirrhosis patients." (PMID 40114845, 2025). "While LBP is increased in patients with ascites and hyperdynamic circulation and is of some prognostic significance in cirrhosis, in a recent study it was not significantly regulated across the stages of cirrhosis as compared to CRP, IL‐6, or procalcitonin in line with our findings." (PMID 40317887, 2025). "Patients with cirrhosis typically have higher basal CRP levels than those without cirrhosis." (PMID 37559036, 2023). "Interestingly, a negative association of CRP and PCSK9 existed in HCV-infected patients with cirrhosis before therapy and at 12 weeks posttreatment." (PMID 33920491, 2021). "The C-reactive protein (CrP) level, which is a global marker for inflammation, was higher in individuals with cirrhosis, and the hemoglobin level was significantly better in patients without cirrhosis." (PMID 29897895, 2018). "This hypothesis is based on the findings of increased leukocyte count and C-reactive protein (CRP) levels in patients with ACLF compared to those of patients with cirrhosis without ACLF and their correlation with prognosis." (PMID 27578545, 2016). "In non-cirrhosis patients, none of the SM species correlated with the MELD score, ALT, AST, bilirubin, albumin, INR, CRP, leukocytes, platelets, or creatinine." (PMID 37176109, 2023). "Regarding the effect of rifaximin on CRP and CAR, rifaximin improves CRP levels in small intestinal bacterial overgrowth, whereas no studies have examined CRP or CAR in cirrhosis." (PMID 36983211, 2023). "In recent years, serum CRP and PCT have been suggested for diagnosis and prediction of bacterial infection in chronic liver disease, with or without cirrhosis." (PMID 29623264, 2018). "Zonulin and calprotectin in stool were not distinct between groups, but CRP was significantly higher in SC-CIP and CIP controls compared to healthy and in SC-CIP patients compared to cirrhosis (SC-CIP–healthy: p < 0.001; CIP controls–healthy: p = 0.016; Cirrhosis–SC-CIP: p = 0.04)." (PMID 32906634, 2020). "Significant positive correlation was documented between the MDA level and de Ritis coefficient (AST/ALT), a marker of liver damage severity; between MDA and inflammation (CRP); between MDA and NOx concentration in the groups with cirrhosis with and without HRS." (PMID 29658815, 2018).
vitamin D deficiency (140 papers, 2008 to 2026). A nutritional condition produced by a deficiency of VITAMIN D in the diet, insufficient production of vitamin D in the skin, inadequate absorption of vitamin D from the diet, or abnormal conversion of vitamin D to its bioactive metabolites. "Vitamin D deficiency was defined as serum 25(OH)D < 20 ng/mL, and high inflammation as CRP ≥ 3 mg/L." (PMID 41599837, 2026). "Mediation analysis confirmed that vitamin D deficiency mediated dietary intake-CRP and dietary intake-ferritin links (Sobel test p < 0.05)." (PMID 41599837, 2026). "Analysis of inflammatory markers further strengthened the association: CRP positivity was highest among neonates with severe vitamin D deficiency (≤10 ng/mL), while those with higher vitamin D levels (30-100 ng/mL) had markedly lower CRP positivity (30%)." (PMID 41531449, 2026). "The Venn diagram ultimately acquires eight core targets for machine learning: disease course, leukocytes, neutrophils, lymphocytes, monocytes, CRP, ferritin, and vitamin D deficiency." (PMID 40852518, 2025). "Significant differences were seen between the CD remission and active CD groups in terms of C-reactive protein (p = 0.04), vitamin D deficiency (p=0.02) and vitamin D sufficiency (p=0.01), and abdominal surgery (p=0.04)." (PMID 40808950, 2025). "Regarding CRP, patients with vitamin D deficiency had a significantly higher mean value (130.00 mg/dL, SD = 83.30) compared to those with optimal vitamin D levels (19.80 mg/dL, SD = 13.91)." (PMID 40217860, 2025). "Based on machine learning, disease duration, white blood cell, neutrophils, lymphocytes, monocytes, CRP, ferritin, and vitamin D deficiency factors were finally obtained and included in the multifactorial logistic regression analysis." (PMID 40852518, 2025). "Vitamin D deficiency is associated with increased inflammation and it has been shown that vitamin D3 supplementation can inhibit the release of CRP, TNF-α, and IL-6." (PMID 40364117, 2025). "It has also been established that vitamin D deficiency enhances inflammation (increase in C-reactive protein (CRP))." (PMID 40869314, 2025). "All groups exhibited higher-than-normal levels of C-reactive protein and fibrinogen, but calcium and vitamin D deficiencies." (PMID 40572667, 2025). "Vitamin D deficiency is a significant correlate of albuminuria in T2D patients, independent of eGFR and basic inflammatory markers including hs‐CRP and TNF‐α." (PMID 40804707, 2025). "The figure demonstrates that patients with vitamin D deficiency have significantly higher CRP levels, indicating a more pronounced systemic inflammatory response compared to those with optimal vitamin D levels." (PMID 40217860, 2025). "Patients with vitamin D deficiency exhibited significantly higher CRP values compared to those with optimal vitamin D levels (130.00 mg/dL vs. 19.80 mg/dL, p = 0.001), indicating a pronounced systemic inflammatory response." (PMID 40217860, 2025). "A recent study found that vitamin D deficiency is associated with higher C-reactive protein (CRP) levels, and patients with low serum vitamin D and high CRP levels are at a higher risk of developing the universalis form of AA." (PMID 40026917, 2025). "In our study, CRP, an indicator of acute inflammation, increased in children with IR and vitamin D deficiency and insufficiency." (PMID 39275320, 2024). "In our study, it has been shown that gallstone formation is more common in vitamin D deficiency and high levels of CRP." (PMID 38394521, 2024). "The England Longitudinal of Ageing (ELSA) study reported an association of vitamin D deficiency with elevated levels of CRP (≥ 3 mg/L)." (PMID 37340242, 2023). "Multivariate model assessing ICU admission adjusted for vitamin D deficiency, mortality, age, oxygen administration, hospital vitamin D supplementation, hospital length of stay, peak D-dimer, peak CRP, peak fibrinogen, and peak LDH." (PMID 37575807, 2023).
vitamin D deficiency (continued). "It should be noted that vitamin D deficiency was more strongly correlated with increased IL-6 (r=−0.37) and CRP (r=−0.39), as well as with DI (r=−0.36)." (PMID 37558268, 2023). "In that paper vitamin D promotes the production of IL-10, an anti-inflammatory cytokine and markedly decreases C-reactive protein (CRP) in cases with the most severe vitamin D deficiency." (PMID 37346332, 2023). "One study reported that patients with vitamin D deficiency showed increased serum high sensitivity C-reactive protein (hs-CRP) levels." (PMID 35236423, 2022). "Group 1 (vitamin D deficiency) and group 2 (vitamin D insufficient) had lower CRP levels when compared to group 3 (vitamin D sufficient) (p = 0.041)." (PMID 34544219, 2022). "Taking into account baseline vitamin D status of the study group (serum 25(OH)D level ≥ 15 ng/ml or < 15 ng/ml), we noticed that in children with severe vitamin D deficiency, 25(OH)D levels were related negatively to CRP levels (R= -0.42, p = 0.017)." (PMID 35769088, 2022). "Previous experimental studies have linked antiangiogenic factors with other maternal serum parameters, such as vitamin D deficiency, increased IL-6 or C-reactive protein, and decreased leptin levels." (PMID 35631313, 2022). "Vitamin D deficiency (<20 ng/mL) was positively associated with log-CRP (adjusted model: β = 0.56, 95% CI 0.10, 1.02, reference group: sufficiency > 30 ng/mL)." (PMID 35057447, 2022). "OS, higher ferritin and CRP levels, lower hemoglobin, hematocrit and prealbumin levels, and vitamin D deficiency represent significant risk factors for EPO resistance development in HD patients." (PMID 35464768, 2022). "Subjects with vitamin D deficiency (< 20 ng/ml) have increased us-CRP and PTH compared with those with insufficiency (20-32 ng/ml) or optimal concentrations (> 32 ng/ml)." (PMID 34991572, 2022). "Specifically, vitamin D deficiency and higher levels of omega 6:3 ratio above the recommended level (>5) are associated with higher levels of CRP in people living with chronic pain." (PMID 35057447, 2022). "There was a significant inverse association between vitamin D as a continuous variable and a positive association for vitamin D deficiency and log-CRP in the chronic pain group." (PMID 35057447, 2022). "In this study, high CRP levels and bioavailable vitamin D deficiency significantly increased remnant cholesterol levels in the non-diabetic group." (PMID 33728195, 2021). "We also previously showed that vitamin D deficiency was associated with a more pronounced pro-inflammatory status, including higher Interleukin (IL)-6 and C-reactive protein (CRP) in older Irish adults." (PMID 33672800, 2021). "Vitamin D deficiency and elevated high sensitivity C-reactive protein (hs-CRP) have been associated with several health outcomes, but knowledge on early life trajectories and association between 25 hydroxyvitamin D (25(OH)D) and hs-CRP is lacking." (PMID 35010890, 2021). "Combination of severe vitamin D deficiency and high CRP was associated with a higher chance to have CVD (OR = 2.69, 95% CI = 1.45‐4.98, P = .0017)." (PMID 31020672, 2019). "Participants with high CRP levels and severe vitamin D deficiency had a higher likelihood of having CVD than those with neither risk factor (odds ratio = 2.69, 95% confidence interval = 1.45‐4.98, P = .0017)." (PMID 31020672, 2019). "A research on a cohort of 201 CD patients in Canada stated that CRP was significantly lower in patients with vitamin D deficiency." (PMID 30647532, 2018). "In summary, vitamin D deficiency was significantly associated with a higher hs-CRP level than all of the other three categories of vitamin D status." (PMID 29023388, 2017). "Those with vitamin D deficiency (serum 25-OHD levels <10 ng/ml) had mean CRP levels of 7.8 (SD 10.4) mg/L, significantly higher than those who were not vitamin D deficient (serum CRP of 3.9 (SD 4.3) mg/L (t = 3.789, p < 0.001)." (PMID 27000113, 2016).
vitamin D deficiency (continued). "Abnormal vascular smooth muscle cell proliferation has been shown to increase the production of acute-phase reactant proteins like CRP, while Vitamin D deficiency has been implicated in cardiovascular disease." (PMID 24736319, 2014). "In our study, rates of positive blood culture and of MODS were higher among patients with vitamin D deficiency than among those with vitamin D sufficiency; deficient patients also tended to have higher CRP levels." (PMID 24073266, 2013). "Significant association with higher mean serum glucose levels and mean CRP levels was noted in 25 hydroxy vitamin D deficiency group." (PMID 24455278, 2013). "Vitamin D deficiency is associated with increased circulating inflammatory proteins, and vitamin D status seems to modulate C-reactive protein levels." (PMID 22470291, 2012). "Multivariable analysis showed vitamin D deficiency (adjusted OR 7.1; 95% CI 2.5-19.4; p < 0.001) and hyperferritinemia (ferritin ≥ 200 μg/L; aOR 8.0, 95% CI 3.5-18.2, p < 0.001) as predictors of high CRP." (PMID 41599837, 2026). "Mediation analysis assessed whether vitamin D deficiency mediated the link between dietary intake and high CRP or ferritin." (PMID 41599837, 2026). "In this cross-sectional study of RA patients with shoulder pain, abnormal HRUS findings were common and were significantly predicted by hematologic and metabolic parameters, particularly lower hemoglobin and higher PLT counts, with ESR, CRP and vitamin D deficiency also contributing." (PMID 41602254, 2026). "Furthermore, vitamin D deficiency (<20 ng/mL) was associated with a 3.5-fold increase in CRP compared to levels ≥ 20 ng/mL (p = 0.012)." (PMID 41829997, 2026). "Subgroup analysis demonstrated that nutritional vitamin D supplementation not only reduced CRP in MHD patients with baseline vitamin D deficiency, but also in those with normal vitamin D baseline levels [MD -2.64, 95% CI (-4.47, -0.81), P < 0.05; MD -3.97, 95% CI (-5.78, -2.17), P < 0.05]." (PMID 42293210, 2026). "The results showed that disease duration, leukocytes, neutrophils, lymphocytes, mono-CRP, ferritin, and vitamin D deficiency, were independent risk factors for the diagnosis of BPPV (OR>1, p < 0.05), and monocyte count was an independent protective factor for the diagnosis of BPPV (OR<1, p < 0.05)." (PMID 40852518, 2025). "Vitamin D deficiency was also linked to a more intense systemic inflammatory response, as reflected by significantly elevated C-reactive protein (CRP) levels, which may contribute to the severity of oropharyngeal infections." (PMID 40217860, 2025). "There was a significant interaction between vitamin D deficiency and CRP z-score (p < 0.001)." (PMID 39662157, 2025). "The results of regression analysis showed that disease duration, white blood cell count, neutrophil count, lymphocyte count, CRP, ferritin and vitamin D deficiency were independent risk factors for the diagnosis of BPPV, while monocyte count was an independent protective factor." (PMID 40852518, 2025). "Integration of the results of the two methods through Venn diagrams resulted in the identification of eight core features, including disease duration, white blood cell count, neutrophil count, lymphocyte count, monocyte count, CRP, ferritin, and vitamin D deficiency." (PMID 40852518, 2025). "Additionally, obese patients with pronounced vitamin D deficiency exhibited elevated levels of C-reactive protein (CRP), as indicator of the associated low-grade systemic inflammation." (PMID 40261445, 2025). "Patients with vitamin D deficiency had higher CRP levels (64.41% vs. 35.59%; p = 0.000)." (PMID 39200151, 2024). "Vitamin D deficiency was more prevalent in CRP > 5 mg/dL patients." (PMID 39200151, 2024). "The observed association between 25(OH)D and CRP is likely to be caused by vitamin D deficiency, and correction of low vitamin D status may reduce chronic inflammation." (PMID 37168807, 2023).